UHRF2 (ubiquitin like with PHD and ring finger domains 2)
Diseases named in the same sentence as UHRF2 in open-access papers (continued):
Sharing a sentence is not in itself a finding about the gene and the disease.
lymphoma (1 paper, 2016). A malignant (clonal) proliferation of B- lymphocytes or T- lymphocytes which involves the lymph nodes, bone marrow and/or extranodal sites. "We show examples of significant reduction in UHRF2 staining in pancreatic, lymphoma, cervical, endometrial, squamous cell carcinoma (SCC) and head & neck human tumors." (PMID 27738314, 2016).
melanoma (1 paper, 2018). A malignant, usually aggressive tumor composed of atypical, neoplastic melanocytes. "UHRF2 protein expression levels in our western blots were not correlated with changes in global methylation or PD-L1 expression, although additional investigations of the relationship between UHRF2, DNMT3A, PD-L1, and global hypomethylation in melanoma may still be warranted." (PMID 30240750, 2018).
Parkinson disease (1 paper, 2024). A progressive degenerative disorder of the central nervous system characterized by loss of dopamine producing neurons in the substantia nigra and the presence of Lewy bodies in the substantia nigra and locus coeruleus. "Using this pipeline for genes in Parkinson’s disease with oxidative stress revealed two unexploited genes: nuclear protein 1 (NUPR1) and ubiquitin-like with PHD and ring finger domains 2 (UHRF2)." (PMID 39154038, 2024).
posterior fossa ependymoma (1 paper, 2022). A high grade ependymoma that is located within the posterior fossa. "Interestingly, 6/7 of the constrained genes in which pLoF variants were found in patients with posterior fossa ependymoma show particularly high expression levels in cerebellar tissue (UHRF2, FOXO3, CDC42BPA, ZMYM2, CHD6 and DNAJC2)." (PMID 36008825, 2022).
pulmonary hypertension (1 paper, 2025). Increased pressure within the pulmonary circulation due to lung or heart disorder. "Alternatively, UHRF2 may take part in pulmonary vaso‐occlusions, which underlie the occurrence of pulmonary hypertension." (PMID 41047474, 2025). "If confirmed in other large cohorts, our finding of variations in UHRF2 as a potential marker of disease severity, associated epigenetic modulation and pulmonary hypertension may help identify these higher‐risk individuals." (PMID 41047474, 2025). "suggests a possible role for UHRF2 in the pathogenesis of pulmonary hypertension, one of the more severe organ complications presented by patients with SCD." (PMID 41047474, 2025).
T-cell leukemia (1 paper, 2016). A malignant disease of the T-lymphocytes in the bone marrow, thymus, and/or blood. "Among the ALL-T cell leukemias, which all were strongly methylated in this region, 2 of the 5 showed a reduction in UHRF2 protein levels by IHC and immunoblotting." (PMID 27738314, 2016).
testis cancer (1 paper, 2016). "We show an example of a highly proliferative, 5hmC− testis cancer where UHRF2 levels are observed at moderate levels primarily in the nucleus." (PMID 27738314, 2016). "Testicular cancer is thought to arise from germ cells, and these cells displayed strong nuclear UHRF2 staining in normal tissue." (PMID 27738314, 2016). "Lastly, UHRF2 protein levels are also reduced in a highly Ki67+ testis cancer." (PMID 27738314, 2016).
viral infection (1 paper, 2026). "Consequently, UHRF2-deficient mice exhibit profound resistance to lethal virus infection in vivo due to IFN-I overproduction." (PMID 42212328, 2026). "During viral infection, activated TBK1 undergoes nuclear translocation, where it is hijacked by UHRF2 to achieve gene-specific targeting at IFN-I loci." (PMID 42212328, 2026).
tumor (20 papers, 2012 to 2025). "In further support of this conclusion, we demonstrated that overexpression of wild type but not enzymatic activity-deficient DNMT3A mutant phenocopied the impaired tumor growth result observed for UHRF2 knockdown A549 cells." (PMID 27462454, 2016). "We sought to determine if loss of UHRF2 expression was a recurring theme in other human tumor types." (PMID 27738314, 2016). "Loss of UHRF2 is associated with progression of cancer and UHRF2 is a negative regulator of epithelial–mesenchymal transition, suggesting the role of UHRF2 as a tumor suppressor." (PMID 37628583, 2023). "Immunohistochemistry staining for DNMT3A confirmed increased levels of DNMT3A in the tumors derived from the shUHRF2-expressing A549 cells, indicating that increased DNMT3A levels upon downregulation of UHRF2 are associated with drastically reduced tumor growth." (PMID 27462454, 2016). "Loss of UHRF2 expression has been implicated in neoplasia, where alterations in its ability to recognize and interpret 5hmC may contribute to promoter hypermethylation, disrupted gene expression, and tumor progression." (PMID 41516186, 2025). "TRIM8 and UHRF2 expression in the tumor group was significantly higher than that in the normal group." (PMID 38879525, 2024). "UHRF2 has also been reported to affect certain phenotypes of tumor cells through DNA demethylation, the ErbB3/Ras/Raf signaling pathway, and the Wnt/β-catenin signaling pathway." (PMID 38879525, 2024). "The CPTAC (Clinical Proteomic Tumor Analysis Consortium) database was used to analyze the prognosis of HBV-positive patients with different UHRF2 protein levels." (PMID 36690646, 2023). "The results showed significantly greater tumor growth in UHRF2-overexpressed cells, and the co-overexpression of HBx and UHRF2 further contributed to this effect." (PMID 36690646, 2023). "UHRF2 and ectopic HBx expression were also measured in the xenografted tumor by immunohistochemistry and immunofluorescence." (PMID 36690646, 2023). "In contrast to UHRF1, UHRF2 exhibits tumor-suppressor gene capacities, but an ability to favor tumor progression cannot be excluded, at least in certain types of cancer, such as hepatocellular carcinoma or intestinal tumorigenesis." (PMID 37630248, 2023). "So, at present, it seems that UHRF2 plays roles as both oncogene and tumor suppressor depending on the cancer cell type." (PMID 31245293, 2019). "We used IHC on human tumor specimens (160 from 19 tumor types) or normal tissue to determine the expression and distribution of UHRF2, Ki-67, and 5hmC." (PMID 27738314, 2016). "Normal tissue was arranged into tissue microarrays (TMAs) so that staining with anti-UHRF2 antibodies was conducted simultaneously on normal, and tumor tissues." (PMID 27738314, 2016). "Our previous analysis of UHRF2 expression in normal vs. cancer tissue indicated that its levels are decreased in a wide variety of human tumor types." (PMID 27738314, 2016). "Notably, UHRF2 total expression remained consistent between tumor stage I and normal samples, bolstering the validity of the bioinformatic observation as it does not depend on total changes in gene expression." (PMID 38539439, 2024). "In contrast, UHRF2 is downregulated in various cancers, suggesting that UHRF2 may play a role as a tumor suppressor." (PMID 37628583, 2023). "Each of the different tumor types displayed a unique UHRF2 methylation pattern." (PMID 27738314, 2016). "Although UHRF2 was expressed at a relatively low level in both tumor samples and controls, increased UHRF2 proteins could be detected in 4 out of 10 tumor samples." (PMID 27462454, 2016). "These researches supported our results that UHRF2 might play an oncogenic role in tumor." (PMID 34400880, 2021). "Thus it is possible that our tumor samples with high UHRF2 expression have hydryxomethylated promoters which might cause increased gene expression even though they were detected as hypermethylated." (PMID 27738314, 2016).
tumor (continued). "Finally, UHRF2 frequently displays a significant reduction in expression in diverse tumor types." (PMID 27738314, 2016). "Furthermore, as knockdown of UHRF2 in A549 cells led to reduced cell proliferation and impaired tumor growth, our data support a positive link between DNA hypomethylation and tumor growth." (PMID 27462454, 2016). "The expression levels of three writers (DNMT1, DNMT3A, DNMT3B), two erasers (TET1, TET3), and eight readers (MBD4, ZBTB33, UHRF1, UHRF2, UNG, TDG, NTHL1, SMUG1) were dramatically higher in tumor tissues (p < 0.05)." (PMID 38317133, 2024). "The expression of UHRF2 in HBV-positive HCC tumors and non-tumor tissues was investigated to determine its biological role." (PMID 36690646, 2023). "Significantly, by analyzing the unrestricted paired tumor and normal control RNA-seq data available in the TCGA database, UHRF1 and to a less extent UHRF2 are found to be substantially overexpressed in all types of cancers." (PMID 27462454, 2016). "This allowed us to determine if UHRF2 is expressed in differentiated and/or proliferating normal tissue and if it is expressed in or absent from Ki67 positive regions of tumor sections." (PMID 27738314, 2016). "Functional impairment of HSPCs associated with Uhrf2 deletion may be compatible with the roles of Uhrf2 in proliferation of other progenitors rather than with tumor suppressive roles." (PMID 37628583, 2023). "Considering the high expression of DNMT3A, TET1, DNMT3B, TET3, UHRF2, DNMT1, UHRF1and TDG in Subtype B, changing the tumor microenvironment cell infiltration characteristics by reversing expression of these DNA methylation regulators may be more clinically practical." (PMID 35771147, 2022). "Interestingly, several are suggested to have tumor suppressor roles (FOXO3, TRIM67, UHRF2, CHD6)." (PMID 36008825, 2022). "This analyses documented UHRF2 expression across a variety of normal and tumor solid tissues, but had not assessed the presence of UHRF2 in normal or malignant hematological cells, so we assessed relative levels of UHRF2 in hematopoietic stem cells, progenitors or differentiated cells." (PMID 27738314, 2016). "However, in some tumoral cell lineages, UHRF1 and UHRF2 exerted negative transcriptional influence on the expression of p2150." (PMID 31024001, 2019).
cancer (14 papers, 2015 to 2024). A tumor composed of atypical neoplastic, often pleomorphic cells that invade other tissues. "A high level of UHRF2 is considered to be associated with a poor prognosis in many cancers, and its auto-ubiquitylation properties result in generally low and unstable protein levels in cells and tissues." (PMID 36690646, 2023). "Emerging evidence revealed that UHRF2 was implicated in a variety of human diseases, especially in cancer." (PMID 34400880, 2021). "We investigated the mechanism underlying UHRF2-mediated regulation of H3K9ac and H3K14ac expression and the factors associated with differential regulation in normal and cancer cells." (PMID 27743347, 2017). "We suggest that phosphorylation of UHRF2 acts as a “switch” in the disease process, allowing UHRF2 to play a bi-faceted role in cancer." (PMID 36690646, 2023). "UHRF1 and UHRF2 proteins share a highly similar structural homology with each other, but the expressions of these proteins are different in cancers." (PMID 37628583, 2023). "The UHRF2 protein levels were upregulated in HBV-positive HCC cancer tissues compared to para-cancerous tissues." (PMID 36690646, 2023). "Ubiquitin-like with PHD and ring finger domains (UHRF2) is a ubiquitin-protein E3 ligase that plays multiple roles in cancer development." (PMID 36690646, 2023). "The different expression patterns of UHRF2 in cancers revealed the complexity of the function of UHRF2 and its importance in tumorigenesis." (PMID 34400880, 2021). "In summary, the findings suggest that UHRF2 mediated the post-translational modification of histones and the initiation and progression of cancer." (PMID 27743347, 2017). "In normal cells, UHRF2 overexpression enhances the expression of H3K9ac and H3K14ac, which is reversed in cancer cells." (PMID 27743347, 2017). "We previously demonstrated that UHRF2 regulated H3K9ac and H3K14ac differentially in normal and cancer cells." (PMID 27743347, 2017). "Second, UHRF2 protein levels are significantly reduced or mislocalized in a wide variety of human cancers compared to normal tissue." (PMID 27738314, 2016). "Together, these findings indicate that UHRF2 and 5hmC are widely present in differentiated human tissues, and UHRF2 protein is poorly expressed or mislocalized in diverse human cancers." (PMID 27738314, 2016). "In contrast, UHRF2 immunostaining in human cancer tissues revealed widespread reduction or abnormal cytoplasmic localization which correlated with a higher Ki-67 and reduced 5hmC." (PMID 27738314, 2016). "UHRF2 is a ubiquitin-protein ligase E3 and is involved in the development of many cancers." (PMID 36690646, 2023). "UHRF2 functioned as a positive or negative regulator in various cancers, including CRC." (PMID 37370759, 2023). "Therefore, this study focuses on the regulation of UHRF2 phosphorylation levels in specific cancer processes." (PMID 36690646, 2023). "Thus, UHRF2 and 5hmC are widely present in differentiated human tissues, and UHRF2 protein is poorly expressed or mislocalized in diverse human cancers." (PMID 27738314, 2016). "UHRF2 is a potential tumor suppressor gene located within the 9p24 chromosomal region which is among the most frequent sites of DNA copy number lost in human cancer." (PMID 27738314, 2016). "Although UHRF2 is less frequently overexpressed in cancers in comparison with UHRF1 and is therefore less responsible for downregulation of DNMT3A in cancers, in a few cancer cell lines, especially A549, UHRF2 appears to play a dominant role in negative regulation of DNMT3A." (PMID 27462454, 2016). "Another subset of these cancers showed a significant increase in cytoplasmic localization of UHRF2." (PMID 27738314, 2016). "For example, in silico analyses were performed for some alternatively spliced proteins with reported antagonistic functions in cancer, including BRD4, KLF4, and UHRF2." (PMID 38539439, 2024).
cancer (continued). "In this study, we found that UHRF2 regulated H3K9ac and H3K14ac expression via YDG and RING finger domain, and contrasting results were found in normal and cancer cells." (PMID 27743347, 2017). "In cancer cells, ablation of TIP60 and UHRF2 overexpression further decreased H3K9ac and H3K14ac protein levels." (PMID 27743347, 2017). "In cancer cells, the degradation of TIP60 was accelerated by UHRF2." (PMID 27743347, 2017). "Interestingly, the differential regulatory mechanism of UHRF2 against TIP60 in normal and cancer cells attracted our attention and investigation." (PMID 27743347, 2017). "To test if UHRF1/2 overexpression indeed leads to downregulation of DNMT3A proteins in cancers despite DNMT3A overexpression at the level of transcription, we next examined the levels of UHRF1, UHRF2 and DNMT3A proteins in paired lung tumors and adjacent normal controls by western blot analysis." (PMID 27462454, 2016). "Also in agreement with the observed widespread overexpression of UHRF1 in cancers, our data suggest that UHRF1 is likely to have a broader role in negative regulation of DNMT3A than UHRF2." (PMID 27462454, 2016). "Thus, both UHRF1 and UHRF2 negatively regulate de novo DNA methylation by targeting DNMT3A degradation in both normal somatic and cancer cells." (PMID 27462454, 2016). "Together, these results suggest that, unlike UHRF1, UHRF2 negatively regulates DNA methylation in various human cancer cell lines." (PMID 27462454, 2016). "Having established that both UHRF1 and UHRF2 target DNMT3A for degradation and that downregulation of DNMT3A correlates with DNA hypomethylation, we next investigated the expression profiles of UHRF1 and UHRF2 in various cancers." (PMID 27462454, 2016). "However, UHRF2 is not functionally redundant in maintaining DNA methylation and, unlike UHRF1, the expression of UHRF2 in human cancers tends to be low due to mutation, copy number loss, or CpG hypermethylation of the promoter region." (PMID 36077796, 2022). "However, the protein levels of H3K9ac and H3K14ac were not rescued by the co-expression of TIP60 and UHRF2 in cancer cells." (PMID 27743347, 2017). "While UHRF2 could not only interact with other Ub/UBL-related proteins that regulate Ub/UBL protein modification, it could also interact with PCNA, DNMT1, HDAC1, and TRDMT1, which participate in DNA replication, cell cycle progression, microRNAs in cancer, etc.." (PMID 38879525, 2024).
hematologic malignancy (2 papers, 2016 to 2023). "Despite some alteration of gene expressions, deletion of UHRF2 did not cause hematologic malignancy or confer a growth advantage of HSPCs." (PMID 37628583, 2023). "We thought that differential hypermethylation of the UHRF2 promoter might reasonably explain its reduced levels in human solid and hematological malignancies." (PMID 27738314, 2016).
neurodegenerative disease (1 paper, 2021). A disorder of the central nervous system characterized by gradual and progressive loss of neural tissue and neurologic function. "We focused on Uhrf2, a nuclear protein, because it is expressed in many regions of the CNS, including cortex, and it has been implicated in other neurodegenerative diseases with aggregate formation." (PMID 33670299, 2021).
neurological diseases (1 paper, 2024). "The identification of specific DEGs related to synaptic plasticity and neurotransmission opens new avenues for further investigation into the role of Uhrf2 in hippocampal function and its potential relevance to neurological diseases." (PMID 38338822, 2024). "Targeted investigation of these complex gene regulatory networks mediated by UHRF2 may provide novel insights into neurological disorders characterized by social dysfunction." (PMID 38338822, 2024).
UHRF2 also shares sentences with these, for which no sentence is quoted: esophageal squamous cell carcinoma (3 papers); Anxiety (1); autoimmune disease (1); Burkitt lymphoma (1); cervical cancer (1); chronic myeloid leukemia (1); colorectal adenocarcinoma (1); COVID-19 (1); esophageal cancer (1); hematopoietic cancer (1); infection (1); liver diseases (1); multiple myeloma (1); pancreatic cancer (1); sickle cell disease (1); squamous cell carcinoma (1).